ATXN1 (ataxin 1)
Diseases named in the same sentence as ATXN1 in open-access papers (continued):
Sharing a sentence is not in itself a finding about the gene and the disease.
cervical carcinoma (continued). "In summary, we report the discovery of a novel regulatory mechanism that controls ATXN1 expression as well as the mechanism by which ATXN1 regulates cervical cancer cell EMT." (PMID 28212558, 2017). "Taken together, we propose a model for the role of ATXN1 in the development of cervical cancer cells as follows: ATXN1 promotes the growth of cervical cancer cells through the upregulation of cyclin D1 during the early stages of tumor development." (PMID 29212253, 2017). "The present study provides new insights into the role of ATXN1 in the pathogenesis of cervical cancer." (PMID 28212558, 2017). "We accordingly propose the following model for the role of ATXN1 in cervical cancer cell development according to the results presented herein." (PMID 28212558, 2017). "Together, these results confirm that ATXN1 promotes the proliferation and malignant phenotype of cervical cancer cells by regulating cyclin D1." (PMID 29212253, 2017). "In cervical cancer cells, ATXN1 knockdown induced EMT by directly regulating Snail expression, leading to matrix metalloproteinase activation and the promotion of cell migration and invasion." (PMID 28212558, 2017). "However, Kang and associates reported that ATXN1 inhibited Snail expression, which is a transcription factor for E-cadherin, leading to EMT in cervical cancer." (PMID 34638401, 2021). "We then investigated whether ATXN1 overexpression affected the expression of cyclin D1 in cervical cancer cells." (PMID 29212253, 2017). "We identified the cyclin D1 gene as a downstream target of ATXN1 in cervical cancer cell lines." (PMID 29212253, 2017). "We confirmed that ATXN1 is involved in tumor growth in cervical cancer cells." (PMID 29212253, 2017). "Thus, we found that ATXN1 promotes the proliferation and malignant phenotype of cervical cancer cells by regulating cyclin D1." (PMID 29212253, 2017). "However, ATXN1 and pERK1/2 staining in normal cervical tissues was consistently lower than that in cervical cancer samples." (PMID 29212253, 2017). "Overexpression and downregulation of ATXN1 promoted and impeded the proliferation of human cervical cancer cells, respectively, implying that ATXN1 may function as an oncogene." (PMID 29212253, 2017). "Thus, ATXN1 promotes the growth of cervical cancer cells and the subsequent formation of tumors through the upregulation of cyclin D1." (PMID 29212253, 2017). "Together, our findings indicate that ATXN1 may play a role in the proliferation of cervical cancer cells as well as the growth of tumors." (PMID 29212253, 2017). "Because the role of ATXN1 in cervical cancer remains unclear, we attempted to investigate it in our present study." (PMID 29212253, 2017). "Our results confirm that the EGF pathway is involved in the expression of ATXN1 in cervical cancer." (PMID 29212253, 2017). "Our results show that ATXN1 plays an important role in cervical cancer cell EMT." (PMID 28212558, 2017). "To investigate whether ATXN1 downregulation would induce EMT in cervical cancer cell lines, we used real-time qRT–PCR to determine the expression levels of EMT markers in HeLa and SiHa cells." (PMID 28212558, 2017). "Our results indicate that ATXN1 is an important regulator in the progression of cervical cancer." (PMID 29212253, 2017). "Downregulation of ATXN1 induces the epithelial–mesenchymal transition in cervical cancer cells." (PMID 29212253, 2017). "We further found that ATXN1 knockdown could inhibit cervical cancer cell growth and tumorigenesis." (PMID 29212253, 2017). "We demonstrate that ATXN1 is overexpressed in cervical cancer cells; this overexpression could have been induced by factors such as EGF and that EGF-mediated ATXN1 induction depends on the activation of the EGFR–RAS–MAPK pathway." (PMID 29212253, 2017). "Therefore, the inhibition of ATXN1 and ATXN1-mediated activation of the EGFR–MAPK signaling pathway may play an important role in the treatment of cervical cancer." (PMID 29212253, 2017).
schizophrenia (7 papers, 2011 to 2025). A major psychotic disorder characterized by abnormalities in the perception or expression of reality. "For example, HTT, ATXN1, ATXN7, and CACNA1A were associated with neuropsychiatric disorders such as depression and schizophrenia." (PMID 41254939, 2025). "This miRNA can also inhibit the expression of Ataxin 1 (ATXN1), a gene associated with bipolar disorder, schizophrenia, and major depressive disorder." (PMID 36142403, 2022). "Moreover, it has recently been demonstrated that MiR-144 can inhibit the expression of Ataxin 1 (ATXN1) in human cells, which in turn is associated with mental disorders, such as bipolar disorder, schizophrenia, and major depressive disorder." (PMID 36142403, 2022). "miR-144 can inhibit the expression of ataxin 1 (ATXN1) in human cells, and a search of the Genetic Association Database shows that ATXN1 is associated with mental disorders, such as bipolar disorder, schizophrenia, and major depressive disorder." (PMID 26199675, 2015).
breast carcinoma (6 papers, 2015 to 2025). "From the analysis of the SNPs known to be associated with breast cancer risk, we replicated the previously reported associations with the ATXN1 and ESR1 loci." (PMID 35681745, 2022). "In our previous study, we reported that the ATXN1 regulates E-cadherin expression in MCF-7 breast cancer cells." (PMID 28212558, 2017). "We previously reported that ATXN1 overexpression enhanced E-cadherin expression in the breast cancer cell line MCF-7." (PMID 28212558, 2017). "Recently, ATXN1 was reported to enhance E-cadherin expression in the breast cancer cell line MCF-7, suggesting a potential association between ATXN1 and cancer development." (PMID 28212558, 2017). "ATXN1 showed opposite mRNA patterns against miR-221 in normal breast cell subpopulations, breast cancer cell lines and breast cancer subtypes from the Enerly dataset." (PMID 25686829, 2015). "This is one of the few reports about ATXN1's role in breast cancer." (PMID 25686829, 2015). "We observed that several genes including PTCH1, ATXN1, DLL4, SOX2 and DACH1 were differentially regulated in tbLCM-treated breast cancer cells as compared to those treated with tnLCM or BM control." (PMID 38581619, 2024). "In our previous study, we reported that the overexpression of ATXN1 enhanced E-cadherin expression at the protein and mRNA levels in MCF-7 breast cancer cells." (PMID 28212558, 2017). "Additionally, they include several non-neurological traits or diseases (such as ATXN1, atrial fibrillation; ATXN1/ATXN7, breast cancer; ATXN7, cataracts)." (PMID 41254939, 2025).
attention deficit-hyperactivity disorder (5 papers, 2014 to 2021). A disorder characterized by a marked pattern of inattention and/or hyperactivity-impulsivity that is inconsistent with developmental level and clearly interferes with functioning in at least two settings (e.g. at home and at school). "Indeed, loss or reduction of functional ATXN1 has been observed in patients with autism spectrum disorder and attention-deficit/hyperactivity disorder, suggesting that loss of ATXN1-CIC complexes causes a spectrum of neurobehavioral phenotypes." (PMID 34277598, 2021). "YWHAZ is cocited with FZD7 in a paper on attention-deficit/hyperactivity disorder, with ATXN1 in a paper on the interaction of Akt-Phosphorylated Ataxin-1 with 14-3-3, and with SOS2 in a paper on epidermal growth factor receptor phosphorylation sites." (PMID 25148247, 2014). "Moreover, alteration of the ATXN1-CIC complex determines a spectrum of neurobehavioral phenotypes, including intellectual disability, attention deficit/hyperactivity disorder (ADHD) and autism spectrum disorder." (PMID 32235346, 2020).
developmental delay (5 papers, 2012 to 2021). "Given its importance in brain function and behavior abnormalities in mouse models, we speculate that heterozygous deletions that affect ATXN1 function may be involved with the outcomes of developmental delay and ASDs, either alone or in combination with other gene deletions." (PMID 22480366, 2012). "The deletion found in the SCAP patient harbors ATXN1, DTNBP1, JARID2, and NHLRC1 that we propose may be responsible for ASDs and developmental delay." (PMID 22480366, 2012).
frontotemporal dementia (5 papers, 2016 to 2025). Frontotemporal dementia (FTD) comprises a group of neurodegenerative disorders, characterized by progressive changes in behavior, executive dysfunction and language impairment, as a result of degeneration of the medial prefrontal and frontoinsular cortices. "Frontotemporal dementia was also observed in 12.5% of ATXN1 intermediate allele carrier ALS patients." (PMID 38254109, 2024).
neuroblastoma (5 papers, 2008 to 2025). Neuroblastoma (NB) is the most common solid, extracranial childhood tumor. "Here, we generated human neuroblastoma SH-SY5Y cells with inducible overexpression of the SCA1-causing ATXN1(Q82) isoform and developed a protocol for the efficient isolation of polyQ-expanded ATXN 1 IIBs." (PMID 38125008, 2023). "Furthermore, when EGFP tagged ATXN1 constructs with 2, 30 and 52Q repeats are expressed in neuroblastoma cells they do not bind SAFB1 (unpublished observations)." (PMID 32580238, 2020). "The presence of cytoplasmic polyQ-expanded ataxin-1 is not limited to Cos-7 cells, as cultured neuroblastoma cells such as SH-SY5Y and N2A neuroblastoma cells as well as U343MG astrocytoma cells (data not shown) showed cytoplasmic presence and movement of ataxin-1 accumulations." (PMID 18231590, 2008).
sarcoma (5 papers, 2022 to 2025). A usually aggressive malignant neoplasm of the soft tissue or bone. "In summary, we report three aggressive undifferentiated sarcomas in infants or very young children with novel ATXN1/ATXN1L-associated fusions and gene-expression and methylation patterns similar to that of CIC-rearranged sarcomas." (PMID 35836290, 2022). "Our study confirmed that CIC‐fused and ATXN1‐fused sarcomas presented histopathological and epigenetic similarities, clustering together within the same MC." (PMID 39442927, 2025). "Whereas CIC::LEUTX and CIC::NUTM1 have also been reported in a subset of CIC-rearranged sarcomas, fusions implicating the ATXN1 gene seem to be only encountered in CNS tumors." (PMID 36737790, 2023). "Whatever the type of fusion, a recent study has evidenced that CIC-rearranged sarcomas and ATXN1-rearranged sarcomas of the CNS share the same DNA-methylation signature and are not distinct from their soft tissue counterparts." (PMID 36737790, 2023). "On one hand, fusions of CIC or ATXN1 genes belonging to the same complex of transcriptional repressors, were reported in the CIC‐rearranged, sarcoma (SARC‐CIC)." (PMID 39442927, 2025). "“CIC fused sarcoma” group consisted of CIC::DUX4 (n = 22), CIC break (FISH) (n = 7) and ATXN1::NUTM1 (n = 2)." (PMID 37212486, 2023). "These three cases with novel ATXN1/ATXN1L-associated fusions and features of CIC-rearranged sarcomas may further expand the scope of “CIC-rearranged” sarcomas to include non-CIC rearrangements." (PMID 35836290, 2022). "Additionally, tumors involving ATXN1 rearrangements—such as ATXN1::NUTM1 and ATXN1::NUTM2—may cluster with CIC-rearranged sarcomas by methylation profiling, despite lacking a CIC gene fusion." (PMID 40722508, 2025).
Anxiety (4 papers, 2021 to 2025). Intense feelings of nervousness, tension, or panic often arise in response to interpersonal stresses. "The olfactory receptor genes OR4L1 and OR7H2P are linked to sensory pathways associated with anxiety traits, while ATXN1 (6p22.3) connects cognitive and physical genetic risks." (PMID 40125487, 2025). "ATXN1's role in transcription and neuronal functions suggests potential implications for emotional regulation, with its mutations possibly contributing to anxiety-like behaviors, especially in neurodegenerative contexts." (PMID 40125487, 2025). "Together with that study, our results support the concept that complete loss of ATXN1 causes developmental abnormalities that result in the hyperactivity and attenuated anxiety in mice." (PMID 33436887, 2021). "Together these results indicate that full and partial loss of ATXN1 alter mood phenotype in mice in opposite ways, with partial loss leading to increased anxiety and full loss resulting in decreased anxiety." (PMID 33436887, 2021). "Among which, rs62389045 located in ATXN1 (P = 4.38 × 10− 8, adjusted P = 3.55 × 10− 6) showed the highest OR value of 2.17, implying this genetic variant exhibits the highest risk interacting with birth by CS for anxiety." (PMID 37029353, 2023). "Regarding the molecular mechanism, partial loss of ATXN1 may play a role in anxiety, based on our results for Atxn1 haploinsufficient and null mice." (PMID 33436887, 2021). "On the other hand, 50% loss of ATXN1 function may be well tolerated during development but cause neurobehavioral problems, including anxiety-like behavior, in adulthood." (PMID 33436887, 2021). "To test whether attenuated anxiety ATXN1[82Q] mice is caused by a reduced stress-induction, we examined both basal and restraint stress-induced blood corticosterone levels in ATXN1[82Q] mice and wild-type littermate controls." (PMID 33436887, 2021). "Recent GWAS have also identified seven significant genetic loci—RNU6–168P, MAT2B, DKK2, DIP2C, COL22A1, OR4L1, and ATXN1—that influence anxiety traits in Caesarean-born offspring." (PMID 40125487, 2025). "Particularly, the role of gene-environment interactions in understanding anxiety risks is critical, with genetic variants like DKK2 and ATXN1 showing interactions with CS." (PMID 40125487, 2025). "Purkinje cell limited overexpression of mutant ATXN1 attenuated anxiety in transgenic ATXN1[82Q] mice, whereas global expression of mutant ATXN1 in knock-in mice increased anxiety." (PMID 33436887, 2021). "In fact, ATXN1[82Q] mice-SCA1 transgenic line that overexpresses mutant ATXN1 only in cerebellar Purkinje cells-exhibited attenuated anxiety." (PMID 33436887, 2021). "We found that Atxn1154Q/2Q mice, an SCA1 knock-in line with global expression of mutant ATXN1, exhibit an anxiety-like phenotype on the elevated plus maze." (PMID 33436887, 2021). "The effect of ATXN1 loss-of-function on anxiety in the elevated plus maze was more difficult to interpret—a 50% decrease in ATXN1 expression resulted in a subtle anxiety-like phenotype in Atxn1+/− mice, while full knock-out of ATXN1 slightly attenuated anxiety." (PMID 33436887, 2021). "This suggests that anxiety seen in patients with SCA1 may be, at least in part, caused by underlying pathogenesis from mutant ATXN1." (PMID 33436887, 2021). "This severe Purkinje cell dysfunction may explain the attenuated anxiety in ATXN1[82Q] mice." (PMID 33436887, 2021). "GWEIS revealed multiple suggestive genes interacted with birth by CS for anxiety, such as DKK2 (rs13137764, P = 1.24 × 10− 9, adjusted P = 2.68 × 10− 7) and ATXN1 (rs62389045, P = 4.38 × 10− 8, adjusted P = 3.55 × 10− 6)." (PMID 37029353, 2023). "This anxiety-like phenotype, like motor and cognitive deficits, depends on the length of the polyQ tract: we did not observe increased anxiety in Atxn178Q/2Q mice, another SCA1 knock-in line that globally expresses mutant ATXN1 with fewer polyQ repeats." (PMID 33436887, 2021).
autism (4 papers, 2013 to 2021). Persistent deficits in social interaction and communication and interaction as well as a markedly restricted repertoire of activity and interest as well as repetitive patterns of behavior. "To examine the protein level of the RNAseq results in mouse CAD cells, we tested genes involved in autism risk (NLGN1), neurodegeneration (ATXN1), neurogenesis (REST), embryonic development (TLE4), and neuronal migration (KIF1A)." (PMID 26094033, 2015). "We also observed unique genes for specific subgroups such as TRPV6 for autism or ATXN1 for AS." (PMID 33719335, 2021).
Cognitive impairment (4 papers, 2013 to 2025). Abnormal cognition is characterized by deficits in thinking, reasoning, or remembering. "In this study, we aimed to understand the functional impact of mutant ataxin-1 expression in extra-cerebellar regions and identify potential molecular mechanisms underlying observed clinical phenotypes, including cognitive impairment." (PMID 36078042, 2022). "Patients carrying JARID2 deletion manifested with cognitive impairment, gait disturbance and a characteristic facial appearance, whereas patients with deletion of ATXN1 seemed to be characterized by intellectual disability and behavioural abnormalities." (PMID 23294540, 2013). "Notably, miR-144 appeared to be highly associated with the aging progression, neurodegenerative disorders and cognitive disorders by regulating the expression of ataxin 1 (ATXN1) at post transcription level." (PMID 28938628, 2017). "A key pathogenic factor is the toxic effect of mutant ATXN1: ATXN1 knockout in mice does not cause an ataxic phenotype but leads to mild cognitive impairment, indicating an excess acquisition of pathological function rather than a simple loss of normal protein activity." (PMID 41463080, 2025).
multiple sclerosis (4 papers, 2021 to 2025). A progressive autoimmune disorder affecting the central nervous system resulting in demyelination. "Wild type ATXN1 was recently shown to have a protective role in regulating severity of experimental autoimmune encephalomyelitis (EAE), a well-established mouse model for Multiple sclerosis (MS)." (PMID 40321775, 2025).
Intellectual disability (3 papers, 2013 to 2020). "ATXN1 is involved in the transcriptional repression of the CIC (Capicu transcriptional repressor) protein, and de novo mutations in CIC have been reported to occur in intellectual disabilities, attention deficit/hyperactivity disorder (ADHD), and ASD." (PMID 33374967, 2020). "ATXN1 haploinsufficiency therefore seems to result in intellectual disability with high risk of behavioural abnormalities, but not necessarily ASDs." (PMID 23294540, 2013).
mental disorder (3 papers, 2011 to 2022). A disease that has its basis in the disruption of mental process. "In addition, this study did provide tentative support for a role of the ATXN1 and TRIM31 genes in previously associated linkage areas for intelligence in the context of a psychiatric disorder, that is, ADHD." (PMID 21302343, 2011). "Associations between intelligence and SNPs in the ATXN1 and TRIM31 genes and in three genomic locations showed replicated association, but only in the samples ascertained for ADHD, suggesting that these genetic variants become particularly relevant to IQ on the background of a psychiatric disorder." (PMID 21302343, 2011).
Tremor (3 papers, 2024 to 2025). An unintentional, oscillating to-and-fro muscle movement about a joint axis. "Patient P-1 is a 37-year-old male, carrying 43 repeats in the ATXN1 gene, with tremor onset at a very young age." (PMID 38961870, 2024).
cerebellar disorder (2 papers, 2015 to 2019). Diseases that affect the structure or function of the cerebellum. "Although the molecular mechanisms linking mutant Ataxin-1 to these pathways are unknown, alongside our new data, these findings suggest that metabolic disruption may be a key feature of cerebellar disorders." (PMID 29905912, 2019).
Cerebellar medulloblastoma (2 papers, 2022 to 2025). "In the DAOY cell line (human cerebellar medulloblastoma), the formation of aggregates is reproduced, and the nuclear-cytoplasmic distribution of mutant ATXN1 is studied, as well as the intercellular spread of ATXN1 inclusions." (PMID 41463080, 2025). "In the cell-based screen, we used an ATXN1 reporter Daoy (human cerebellar medulloblastoma) cell line that expressed a bicistronic transgene (mRFP-ATXN1[82Q]-IRES-YFP) to monitor human mutant ATXN1[82Q] levels by measuring the red to yellow fluorescent protein (RFP/YFP) ratio." (PMID 35499073, 2022).